ACAA2 (acetyl-CoA acyltransferase 2)
Diseases named in the same sentence as ACAA2 in open-access papers (continued):
Sharing a sentence is not in itself a finding about the gene and the disease.
osteosarcoma (1 paper, 2023). A usually aggressive malignant bone-forming mesenchymal neoplasm, predominantly affecting adolescents and young adults. "BNIP3 is a unique pro-apoptotic protein with ACAA2 as a functional binding partner in human osteosarcoma U-2OS cells." (PMID 36899330, 2023).
periodontitis (1 paper, 2025). An acute or chronic inflammatory process that affects the tissues that surround and support the teeth. "Furthermore, the downregulation of DBT, ACOX1, ACAA2, and HADHA in the liver provides valuable insights for developing therapeutic strategies for periodontitis-associated NAFLD." (PMID 40951429, 2025). "Based on these findings, DBT, ACOX1, ACAA2 and HADHA emerge as potential key targets linking periodontitis to NAFLD." (PMID 40951429, 2025).
prostate carcinoma (1 paper, 2023). A carcinoma that arises from epithelial cells of the prostate gland. "To assess the profile of ACAA2 expression in prostate cancer tumours, we stained patient tissue microarrays (TMAs) for ACAA2." (PMID 37798372, 2023). "This indicates that ACAA2 level is upregulated in patients with more advanced prostate cancers and positively correlates with prostate cancer progression." (PMID 37798372, 2023). "We also observed that ACAA2 was expressed in ARCaP, which is an AR-low, androgen-repressed prostate cancer cell line that exhibits increased metastatic potential to bones." (PMID 37798372, 2023). "ACAA2 mRNA levels in lung and prostate cancer (PC) patients were assessed in published datasets." (PMID 37798372, 2023). "In addition, consistent with the relationship observed in prostate cancer, ACAA2 mRNA expression also positively correlated with expressions of CHGA and CD56." (PMID 37798372, 2023). "None of the benign prostate tissues, only 2 out of 50 (4%) localised prostate cancer samples, and 10 out of 86 (12%) in adeno-CRPC stained high for ACAA2, which is significantly lower than the 11 out of 27 (41%) of NEPC samples." (PMID 37798372, 2023). "ACAA2 mRNA expression was also elevated in the NEPC cell line, NCI H660, relative to non-SCNC prostate cancers when assessing cell line mRNA levels using data from the Cancer Cell Line Encyclopaedia (CCLE)." (PMID 37798372, 2023).
renal dysfunction (1 paper, 2025). "Given this, we questioned whether modulation of ACAA2 might alleviate myocardial injury in renal dysfunction." (PMID 40149900, 2025).
Renal insufficiency (1 paper, 2025). A reduction in the level of performance of the kidneys in areas of function comprising the concentration of urine, removal of wastes, the maintenance of electrolyte balance, homeostasis of blood pressure, and calcium metabolism. "Nevertheless, it is evident that aerosolized CSNO can partially restore cardiac function in the setting of renal insufficiency and significantly increase ACAA2 protein levels, thereby improving myocardial lipid metabolism." (PMID 40149900, 2025). "In conclusion, this study provides the evidence that myocardial lipid peroxidation is exacerbated under conditions of renal insufficiency and that restoring ACAA2 protein levels can mitigate lipid peroxidation in cardiomyocytes." (PMID 40149900, 2025). "The key fatty acid β-oxidation protein acetyl-CoA acyltransferase 2 (ACAA2) plays a significant role in myocardial lipid peroxidation and cardiac dysfunction induced by renal insufficiency." (PMID 40149900, 2025).
Sepsis (1 paper, 2021). Sepsis is defined as life-threatening organ dysfunction caused by a dysregulated host response to infection. "From the downregulated gene sets, we found downregulation of Acaa2 (Acetyl-CoA acyltransferase 2), which is known to inhibit mammary epithelial cell apoptosis, thus downregulation of Acaa2 during sepsis may increase apoptosis of capEC." (PMID 34638535, 2021).
viral infection (1 paper, 2023). "Interestingly in close parallels to our study emphasizing relationship between the mevalonate pathway and viral infection, previous reports have shown that suppressing HMGCS2 or ACAA2 expression may suppress papillomavirus or poxvirus infection 25,26." (PMID 37369697, 2023).
tumor (14 papers, 2020 to 2025). "Immunoblotting, immunofluorescence, and transmission electron microscopy are performed to investigate the mechanisms underlying LDHC4‐induced ACAA2 lactylation and tumor progression in TNBC." (PMID 40810891, 2025). "ACAA2 was demonstrated as a tumor suppressor and was associated with higher immune infiltration and elevated PD-1 expression of CD8+ T cells." (PMID 36829161, 2023). "LDHC4 overexpression promoted an increase in ACAA2 lactylation both in mouse tumor tissues and MDA‐MB‐231 cells." (PMID 40810891, 2025). "In ACAA2 orthotopic tumor models, both compounds significantly suppressed tumor growth versus controls." (PMID 40810891, 2025). "Among the expression and correlation of the genes, ACAA2 was significantly overexpressed in the tumor tissues and strong correlated with ferroptosis regulators." (PMID 39076986, 2024). "ACAA2 (Acetyl-CoA Acyltransferase 2) catalyzes the last step of the mitochondrial beta-oxidation pathway, and little is known about its roles in tumor genesis and metastasis." (PMID 36829161, 2023). "CCK8, apoptosis analysis, qPCR, subcutaneously implanted murine models and flowcytometry analysis were applied to investigate the roles of ACAA2 in tumor progression and anti-tumor immunity." (PMID 36829161, 2023). "ACAA2 expression was significantly elevated (P = 5.9*10-6) in TD-NEPC tumours with a fold-change of 3 relative to the control, non-SCNC LNCaP tumours in analysis of previously published proteomic profiling." (PMID 37798372, 2023). "In subcutaneously implanted Balb/c murine model, the ACAA2-Overexpression group showed significant tumor growth delay compared to the vehicle group." (PMID 36829161, 2023). "To explore ACAA2’s expression in other tumour types with NE features, we stained ACAA2 in a TMA (NE921) with 20 tumours with NE features, 16 adenocarcinomas, and 8 normal cases." (PMID 37798372, 2023). "Compared with the control group, the higher expression of RPL34-AS1 and ACAA2 were detected in tumor tissues acquiring from RPL34-AS1 overexpression group." (PMID 36162992, 2022). "Our results revealed the tumor-suppressing role of ACAA2 both in vitro and in vivo in RCC." (PMID 36829161, 2023). "Furthermore, we identified and validated the tumor-inhibiting roles of ACAA2, which facilitates the development of diagnosis and treatment for RCC patients." (PMID 36829161, 2023). "Importantly, ACAA2 staining from PDX TMAs of NEPC and adeno-CRPC tumours revealed an increase in ACAA2 protein levels in NEPC when compared to adeno-CRPC PDXs." (PMID 37798372, 2023). "The role of ACAA2 was disrupted in the wild-typeKras gene, which may be due to cetuximab treatment during tumor progression." (PMID 37310146, 2023). "Moreover, we collected 20 RCC tumor samples and 20 adjacent normal samples and observed 75% weak intensity in tumor samples and 90% strong or moderate intensity in normal samples for ACAA2 expression using immunohistochemical analysis, revealing its potential anti-tumor role in RCC." (PMID 36829161, 2023). "Oil Red O staining of MDA‐MB‐231 cells and tumor tissues from nude mice in the LDHC4‐OE and ACAA2‐WT groups revealed that overexpression of either protein increased the number of lipid droplets." (PMID 40810891, 2025). "To validate the positive correlation between ACAA2 expression and the NE phenotype, we analysed three published patient datasets via cBioPortal, and compared ACAA2 mRNA expression in NEPC and adeno-CRPC tumours." (PMID 37798372, 2023). "Clinical samples showed significant downregulation of the following genes: CPT2, ACAA2, HPGD and ALDH3A2, while the expression of ENO2, TDO2, CPOX, ACADL and PTPRG was significantly upregulated in the tumor tissue (p < 0.01)." (PMID 36230866, 2022). "Most of these genes are enzymes in the metabolism of tumor cells, such as HS3ST3B1, GLUD1, BCAT1, and ACAA2." (PMID 32280672, 2020).
tumor (continued). "As our targeted lipid metabolism analysis demonstrated that FFA levels are elevated in ACAA2‐OE MDA‐MB‐231 cells, we further investigated whether LDHC4‐OE or ACAA2‐WT could produce lipid droplets in both MDA‐MB‐231 cells and mouse model tumor tissues." (PMID 40810891, 2025). "Notably, we also found that increased LDHC4 or ACAA2 expression promotes FFA production in MDA‐MB‐231 cells and tumor growth in mouse models." (PMID 40810891, 2025). "Here, we report that ACAA2 expression is increased in SCNCs relative to non-SCNCs in cell lines, tumour xenografts, and patient transcriptomic datasets, suggesting ACAA2 as a potential molecular indicator for these malignancies." (PMID 37798372, 2023). "Tumor tissues were collected for RT-qPCR analysis of RPL34-AS1 and ACAA2." (PMID 36162992, 2022). "Moreover, tumor-infiltrating CD8+ T cells and PD-1 positive CD8+ T cells proportions were higher in the ACAA2-Overexpression group, implying that ACAA2 might serve as a promising immunotherapeutic target in RCC." (PMID 36829161, 2023). "The findings suggest that ACAA2 is significantly lower in CRC tumours with dysregulated RTK expression than in those without, highlighting a potential correlation between ACAA2 and RTK expression." (PMID 37310146, 2023).
cancer (13 papers, 2017 to 2025). A tumor composed of atypical neoplastic, often pleomorphic cells that invade other tissues. "Scd, Scd2, Dgat2, Fads2, Lpin1, Gpat3, Acaa2, Lpcat3, Pcyt2 and Pla2g4a have been reported to be closely associated with cancer." (PMID 35122680, 2022). "The FeFAMscore signature expression level was confirmed using RT-PCR, and ACAA2 progression in cancer was further verified." (PMID 39076986, 2024). "It was reported that ACAA2 decreases fatty acid content through promoting β-oxidation of fatty acids in patients with cancer." (PMID 29310583, 2018). "ACAA2 is associated with cardiovascular risks and lipid metabolism, but its role in cancer has not been fully elucidated." (PMID 37798372, 2023). "Our results confirmed the enhancement of fatty acid biosynthesis pathway and upregulation of Fasn, Ech1, Acaa2 and Hadh, four metabolic genes in the pathway, in KAR cancer cells." (PMID 40621620, 2025). "For example, the methylation regions located in ACAA2, NUSAP1, OGFOD1, PSMD5, SNRNP40, USP37 and XRCC6 are shared by five cancers (i.e., BRCA, CESC, COAD, KIRP and SARC)." (PMID 34464378, 2021). "In the present study, FASN was shown to be upregulated in ACTH-PAs, which was similar to other types of cancer, while enzymes related to fatty acid catabolic metabolism, such as ACADVL, ACADM, and ACAA2, were downregulated in ACTH-PAs." (PMID 30532734, 2018). "Additionally, fatty acid metabolism‐related genes, including Acaa2, Mdh2 and Ech1, as well as oxidative phosphorylation‐related genes, such as Sdhc, Cox5a and Mdh1, also upregulated in KAR cancer cells." (PMID 40621620, 2025). "Both the log-rank test and the univariate Cox regression analysis confirmed that lower expression of CPT2, ACAA2 and ACADM in cancer tissues could predict poor prognosis of CRC patients." (PMID 28977850, 2017). "Based on our result, we hypothesise that ACAA2 has the potential to differentiate cancers with NE features from their non-NE counterparts in SCNCs like NEPC and SCLC." (PMID 37798372, 2023). "However, until now, no related research studies provided any evidence that ACAA2 could have a crucial role during cancer processes." (PMID 32280672, 2020).
infection (5 papers, 2010 to 2021). The state of being infected such as from the introduction of a foreign agent such as serum, vaccine, antigenic substance or organism. "This decreased interaction with SIRT3 aligned with an increase in ACAA2 acetylation levels during infection." (PMID 33857259, 2021). "The SIRT3 interaction with acetyl-CoA acyltransferase 2 (ACAA2), a putative substrate involved in fatty acid beta-oxidation, is lost upon infection, leading to elevated ACAA2 acetylation levels." (PMID 33857259, 2021). "In Cpn group, infection induced down-regulation of acetyl-Coenzyme A acyltransferase 2 (Acaa2, FC = 0.41), ELOVL family member 6, elongation of long chain fatty acids (Elovl6, FC = 0.44), and nuclear receptor subfamily 1, group D, member 2 (Nr1d2, FC = 0.44)." (PMID 24131481, 2013). "Therefore, ACAA2 may have roles in regulating viral or host gene expression during infection, as well as apoptosis." (PMID 33857259, 2021). "The impact of the ACAA2 KD was observed at 24 hpi and maintained throughout the HCMV replication, suggesting a role for ACAA2 early in infection." (PMID 33857259, 2021). "In contrast, well-nourished infected animals exhibited a down-regulation of ECHS1 and ACAA2, suggesting a diminished rate of FAO and a proliferative profile in response to infection." (PMID 31355153, 2019). "The most pronounced interaction change, observed immediately upon infection, was the loss of SIRT3 association (by > 3 fold, not detected at 6, 24, 48, 96, and 120 hpi) with the acetyl-CoA acyltransferase 2 (ACAA2, also known as 3-Ketoacyl-CoA thiolase), a predicted substrate of SIRT3." (PMID 33857259, 2021). "Furthermore, although ACAA2 was reported as a likely SIRT3 substrate, it remains to be demonstrated whether ACAA2 is also a target of SIRT3 enzymatic activity during infection and which acetylation sites are regulated by SIRT3." (PMID 33857259, 2021).
metabolic disease (3 papers, 2021 to 2025). A congenital disorder (due to inherited enzyme abnormality) or acquired (due to failure of a metabolically important organ) disorder resulting from an abnormal metabolic process. "KEGG and Human Metabolome Database (HMDB) enrichment analyses of the differentially abundant lipids suggested that ACAA2 may be associated with adipokine signaling, fat digestion and absorption, the metabolism of various lipid subclasses, and metabolic diseases." (PMID 40810891, 2025).
ACAA2 also shares sentences with these, for which no sentence is quoted: hepatocellular carcinoma (3 papers); Insulin resistance (3); colorectal cancer (2); diabetes (2); energy metabolism disorder (2); ovarian carcinoma (2); adenocarcinoma (1); Alzheimer disease (1); amyloidosis (1); Atrophy (1); cardiovascular disorder (1); cholangiocarcinoma (1); cyst (1); endometriosis (1); esophageal squamous cell carcinoma (1); HCMV infection (1); Hepatitis (1); Huntington disease (1); hyperlipidemia (1); Infertility (1); ischemia (1); lipodystrophy (1); lipomatosis (1); nonalcoholic fatty liver disease (1); Parkinson disease (1); pneumonia (1); renal cell carcinoma (1); serous ovarian cancer (1); tuberculosis (1); uterine cancer (1).